Y_RNA (Y RNA )
Gene: Miscellaneous RNA gene on chromosome 6 (30,932,618 to 30,932,709, reverse strand). Ensembl gene ENSG00000252761.
Homologues: Paralogues in human: Y_RNA (77% identical), RNY1 (76% identical), Y_RNA (76% identical), Y_RNA (75% identical), Y_RNA (74% identical), Y_RNA (73% identical), RNY1P11 (72% identical), Y_RNA (72% identical), RNY1P10 (71% identical), RNY1P12 (71% identical), RNY1P8 (71% identical), Y_RNA (71% identical), and 92 more.